LEMD1 (LEM domain containing 1)
Synonyms: CT50; LEMP-1
Tractability: Antibody: UniProt predicts a signal peptide or a membrane-spanning region; the Human Protein Atlas places it where antibodies can reach.
Gene: Protein-coding gene on chromosome 1 (205,381,378 to 205,455,954, reverse strand). Ensembl gene ENSG00000186007.
Subcellular location: Membrane
Subcellular location (Human Protein Atlas): Plasma membrane
Gene Ontology:
Molecular function: protein binding
Cellular component: membrane
Genetic constraint (gnomAD): Loss-of-function variants: 10 observed, 9.43 expected, observed/expected ratio (o/e) 1.06, 90% interval 0.65 to 1.73. That is too few expected variants to judge how well the gene tolerates losing a copy. Missense variants: 147 observed, 155.37 expected, observed/expected ratio (o/e) 0.95, 90% interval 0.83 to 1.09. Synonymous variants: 66 observed, 60.22 expected, observed/expected ratio (o/e) 1.1, 90% interval 0.9 to 1.35.
Homologues: Orthologues: chimpanzee LEMD1 (99% identical), macaque LEMD1 (89% identical), dog LEMD1 (66% identical), rabbit LEMD1 (62% identical), pig LEMD1 (59% identical), rat Lemd1 (57% identical), mouse Lemd1 (57% identical), zebrafish tmpob (24% identical), zebrafish tmpoa (23% identical), zebrafish lemd1 (22% identical), tropical clawed frog tmpo (20% identical), Caenorhabditis elegans emr-1 (19% identical). Paralogues in human: TMPO (23% identical).
Diseases named in the same sentence as LEMD1 in open-access papers:
LEMD1 is named in the same sentence as 18 diseases in open-access papers, as found by Europe PMC text mining. Sharing a sentence is not in itself a finding about the gene and the disease. The quoted sentences say what the papers report.
colorectal cancer (9 papers, 2008 to 2023). A primary or metastatic malignant neoplasm that affects the colon or rectum. "It has been reported that LEMD1 is aberrantly overexpressed in a series of malignancies and is correlated with worse prognosis of tumor patients such as prostate cancer, colorectal cancer, gastric cancer and pancreatic cancer." (PMID 37296887, 2023). "Transcriptome data has revealed that LEMD1 is highly expressed in cancer stem cells (CSCs)/cancer-initiating cells (CICs) and is important for the maintenance of CSCs/CICs in colorectal cancer." (PMID 37296887, 2023). "High expression of PROM1, LEMD1, CLDN2, PIGR and LCN2 were associated with CRC cell migration, promoting colorectal cancer growth and metastasis." (PMID 36816926, 2023). "Since LEMD1 was first isolated from colorectal cancer in 2004, the role it plays during tumor progression has attracted widespread concern among researchers." (PMID 37296887, 2023). "LEMD1 was shown abnormally upregulated in various kinds of malignancies, such as the oral squamous cell carcinoma, gastric cancer, colorectal cancer and prostate cancer." (PMID 35286235, 2022). "LEMD1 also promotes the initiation and progression of various cancers like colorectal cancer and prostate cancer." (PMID 35983249, 2022). "Emerging evidence supports that LEMD1 is overexpressed and can be regarded as a survival marker of poor prognosis in colorectal cancer." (PMID 35294319, 2022). "Previous studies have shown that LEMD1 is abnormally expressed in oral squamous cell carcinoma, colorectal cancer (CRC), prostate cancer, and anaplastic large cell lymphoma." (PMID 35619906, 2022). "The silencing of LEMD1 dramatically hampered cell growth and enhanced apoptosis in colorectal cancer cells." (PMID 34672237, 2021). "LINC00958 and LEMD1 were found to have increased, while the expression of miR-3064-5p was decreased in colorectal cancer tissues and cell lines." (PMID 34672237, 2021). "Based on the malignant behavior of cancer cells, we investigated the effects of LINC00958/miR-3064-5p/LEMD1 on the viability, proliferation, apoptosis, migration, and invasion of colorectal cancer cells." (PMID 34672237, 2021). "The current study showed that LINC00958 inhibited miR-3064-5p expression and promoted the expression of LEMD1, which effectively enhanced cell growth and arrested apoptosis of colorectal cancer cells." (PMID 34672237, 2021). "To determine the effect of miR-3064-5p-LEMD1 axis in colorectal cancer, we transfected siRNA-LEMD1, miR-3064-5p inhibitor, and NC into HCT116 and HCT8 cells." (PMID 34672237, 2021). "Our study showed that LINC00958 and LEMD1 were upregulated and miR-3064-5p was downregulated in colorectal cancer." (PMID 34672237, 2021). "In our study, LEMD1 expression in colorectal cancer tissues and cells was found to have been significantly increased." (PMID 34672237, 2021). "Overexpression of LEMD1 was also observed during the initiation of colorectal cancer, and downregulation of LEMD1 significantly destroyed the maintenance of colorectal cancer." (PMID 34672237, 2021). "The expression of LINC00958, miR-3064-5p, and LEM domain containing 1 (LEMD1) in colorectal cancer tissues and cell lines was analyzed using reverse transcription quantitative polymerase chain reaction (RT-qPCR)." (PMID 34672237, 2021). "For LEMD1, with the update of studies, its overexpression has been proved in a series of malignancies, such as prostate cancer, oral squamous cell carcinoma, gastric cancer and colorectal cancer." (PMID 35286235, 2022). "This may provide effective biomarkers based on the LINC00958-miR-3064-5p-LEMD1 axis for the treatment of colorectal cancer." (PMID 34672237, 2021). "Notably, we observed that LEMD1 expression was attenuated by the LINC00958-miR-3064-5p axis in colorectal cancer." (PMID 34672237, 2021).
colorectal cancer (continued). "In summary, we uncovered for the first time that LINC00958 sponging miR-3064-5p promotes the viability, proliferation, migration, and invasion of colorectal cancer cells and inhibits apoptosis by elevating LEMD1 expression and activating the PI3K/AKT signaling pathway." (PMID 34672237, 2021). "Our analyses have shown that LINC00958 could facilitate the progression of colorectal cancer by sponging miR-3064-5p and releasing LEMD1, leading to the activation of the PI3K/AKT pathway." (PMID 34672237, 2021). "Thus, miR-3064-5p was observed to attenuate colorectal cancer cell progression by inhibiting LEMD1 expression." (PMID 34672237, 2021). "LINC00958 might promote colorectal cancer progression by repressing the effect of miR-3064-5p on LEMD1 to activate the PI3K/AKT signaling pathway; this may potentially provide therapeutic targets for patients with colorectal cancer." (PMID 34672237, 2021). "Thus, the LINC00958/miR-3064-5p/LEMD1/PI3K/AKT axis was confirmed to influence the progression of colorectal cancer." (PMID 34672237, 2021). "Notably, miR-3064-5p was negatively correlated with LINC00958 or LEMD1 expression in colorectal cancer tissues." (PMID 34672237, 2021). "Moreover, LEMD1 frequently played a key role in the maintenance of cancer-initiating cells (CICs)/cancer stem cells (CSCs) labeled with high capacity of initiation, self-renewal, differentiation and progression in colorectal cancer." (PMID 35286235, 2022). "We have only examined the effects of LINC00958, miR-3064-5p, and LEMD1 on the activity, proliferation, migration, invasion, and apoptosis of HCT116 and HCT8 cells based on the colorectal cancer cell level." (PMID 34672237, 2021). "LEM domain containing 1 (LEMD1) is a type of cancer-testis antigen (CTA) whose expression is highly restricted to testicular germ cells and has been reported to be highly expressed in colorectal cancer." (PMID 35330413, 2022). "Meanwhile, LEMD1 is an activator of PI3K/AKT signaling in gastric cancer and colorectal cancer." (PMID 35294319, 2022). "Notably, LINC00958 inhibited miR-3064-5p and promoted LEMD1; the miR-3064-5p inhibitor abrogated the effect of LINC00958 silencing in colorectal cancer cells." (PMID 34672237, 2021). "The viability, proliferation, migration, invasion, and apoptosis of colorectal cancer cells with silenced LINC00958, miR-3064-5p, and LEMD1 were investigated using the cell counting kit-8 (CCK-8), 5′-Bromo-2′-deoxyuridine (BrdU), flow cytometry, wound healing, and transwell assays." (PMID 34672237, 2021). "A negative correlation between miR-3064-5p and LEMD1 was found in colorectal cancer tissues." (PMID 34672237, 2021). "However, whether the LINC00958-miR-3064-5p-LEM Domain Containing 1 (LEMD1)-phosphatidylinositol 3-kinase (PI3K)/protein kinase B (AKT) axis plays any important role in the onset and development of colorectal cancer remains unclear." (PMID 34672237, 2021). "However, the therapeutic effect of LINC00958/miR-3064-5p/LEMD1, such as exploring the correlation with prognosis, has not been studied at the clinical level, which will be explored in the future studies to provide an effective biomarker for the treatment of colorectal cancer." (PMID 34672237, 2021).
gastric cancer (4 papers, 2021 to 2023). A primary or metastatic malignant neoplasm involving the stomach. "Take cell proliferation for an example, LEMD1 was demonstrated to exacerbate cell proliferation in gastric cancer and thyroid cancer." (PMID 35294319, 2022). "In gastric cancer, upregulated LEMD1 contributes to cancer cell growth, apoptosis and cell cycle via the activation of PI3K/AKT signaling." (PMID 35286235, 2022). "A previous study found that LEMD1 regulates the proliferation and apoptosis of gastric cancer cells by activating the PI3K/AKT signaling pathway." (PMID 34672237, 2021). "For example, the elevated expression of LEMD1 contributes to cell proliferation in gastric cancer." (PMID 37296887, 2023). "The role of LEMD1 has been widely investigated in a variety of human cancers, such as gastric cancer, thyroid cancer, oral squamous cell carcinoma and all results implied that LEMD1 may act as a potent oncogene in cancers." (PMID 35294319, 2022).
oral squamous cell carcinoma (4 papers, 2020 to 2022). "In addition, high expression of LEMD1 is associated with lymph node metastasis and poor prognosis of oral squamous cell carcinoma, and contributes to tumor cell invasion and endothelial transmigration." (PMID 35294319, 2022). "For instance, LEMD1 promotes cell growth, invasion, and endothelial transmigration in oral squamous cell carcinoma (OSCC)." (PMID 34672237, 2021).
pancreatic cancer (3 papers, 2021 to 2023). "LEMD1 also facilitates invasion and epithelial–mesenchymal transition (EMT) in oral squamous cell carcinoma, thyroid cancer and pancreatic cancer." (PMID 37296887, 2023).
prostate carcinoma (3 papers, 2012 to 2022). A carcinoma that arises from epithelial cells of the prostate gland. "Previously, our studies showed expression of TEX101, SPATA19 and LEMD1 in basal cell carcinoma and prostate cancer." (PMID 23396665, 2012).
colon cancer (2 papers, 2022). "Functionally, LEMD1 deficiency impeded the proliferation, migration, invasion and angiogenesis of colon cancer cells." (PMID 35294319, 2022). "LEMD1 was overexpressed in colon cancer tissues and cells and associated with poor prognosis." (PMID 35294319, 2022). "Collectively, LEMD1 induced by SOX4 drove the progression of colon cancer by activating PI3K/Akt signaling." (PMID 35294319, 2022). "Rescue assays validated that SOX4 elevation reversed the suppressive role of LEMD1 deletion in the development of colon cancer and the expression of p-PI3K and p-AKT." (PMID 35294319, 2022). "Correlation analysis of SOX4 and LEMD1 uncovered that SOX4 had a positive correlation with LEMD1 in colon cancer." (PMID 35294319, 2022). "Nevertheless, the specific functions of LEMD1 on the cell malignant phenotypes in colon cancer and the potential regulatory mechanism remain to be figured out." (PMID 35294319, 2022). "In this study, the expression of LEMD1 in colon cancer tissues and prognosis were analyzed using the GEPIA database." (PMID 35294319, 2022). "Further, the expression of LEMD1 in colon cancer cells (LoVo, SW480 and HCT116) was examined by RT-qPCR and western blot." (PMID 35294319, 2022). "Then, the functions of LEMD1 on proliferation, migration, invasion and angiogenesis of colon cancer cells were investigated." (PMID 35294319, 2022). "On the whole, LEMD1 inhibition played the suppressive role in colon cancer proliferation, migration and invasion." (PMID 35294319, 2022). "Functional experiments also confirmed that the suppressive role of LEMD1 knockdown in the proliferation, migration, invasion and angiogenesis of colon cancer cells was reversed by elevation of SOX4." (PMID 35294319, 2022). "It is worth mentioning that LEMD1 expressed at a notably high level was relevant to an unfavorable overall survival and disease-free survival of patients with colon cancer." (PMID 35294319, 2022). "GEPIA database analyzed LEMD1 expression in colon cancer tissues and prognosis of colon cancer patients." (PMID 35294319, 2022). "LEM domain containing 1 (LEMD1) is supposed to be a survival marker of poor prognosis in colon cancer." (PMID 35294319, 2022). "It has been reported that LEMD1 is a survival marker of poor prognosis in colon cancer." (PMID 35294319, 2022). "Meanwhile, SOX4 and LEMD1 had a positive correlation in colon cancer tissues and cells." (PMID 35294319, 2022). "All in all, SOX4 could bind to LEMD1 promoter and positively regulated LEMD1 expression in colon cancer cells." (PMID 35294319, 2022). "Moreover, LEMD1 exhibited higher expression in colon cancer patients with Stage III and IV than in stage I and II." (PMID 35294319, 2022). "More importantly, LEMD1 is supposed to be a survival marker of poor prognosis in colon cancer." (PMID 35294319, 2022). "Taken together, LEMD1 mediated by SOX4 drove the progression of colon cancer." (PMID 35294319, 2022). "Besides, LEMD1 expression differed based on pathological stages of colon cancer, as evidenced by the fact that LEMD1 exhibited higher expression in colon cancer patients with Stage III and IV than in stage I and II." (PMID 35294319, 2022). "Briefly, LEMD1 mediated by SOX4 exacerbated angiogenesis in colon cancer." (PMID 35294319, 2022). "However, this study mainly focused on the bioinformatic analysis and in vitro experiments to explore the effects of LEMD1 in colon cancer." (PMID 35294319, 2022). "The subsequent experiments were performed to further investigate whether LEMD1 affected colon cancer angiogenesis was regulated by SOX4." (PMID 35294319, 2022). "To summarize, LEMD1 was aberrantly expressed in colon cancer and might be an independent factor for overall survival of colon cancer patients." (PMID 35294319, 2022). "LEMD1 was specifically expressed in colon cancer tissues relative to normal tissues." (PMID 35294319, 2022).
colon cancer (continued). "However, the specific functions of LEMD1 on the cell malignant phenotypes in colon cancer remain to be elucidated." (PMID 35294319, 2022). "In the subsequent in vitro experiments, after LEMD1 was depleted, the proliferation of colon cancer cells was observably impeded, as accompanied with the declined protein levels of proliferation markers Ki-67 and PCNA and invasion- and migration-related factors MMP2 and MMP9." (PMID 35294319, 2022). "We aimed to explore the role and mechanism of LEMD1 in colon cancer progression." (PMID 35294319, 2022). "In a word, silencing of LEMD1 played an anti-angiogenesis role in colon cancer." (PMID 35294319, 2022). "Anyway, whether SOX4 binds to LEMD1 in colon cancer remains elusive." (PMID 35294319, 2022). "Also, high expression of LEMD1 predicted a lower overall survival rate and disease-free survival rate of colon cancer patients, suggesting that LEMD1 could be used as a prognostic marker for colon cancer." (PMID 35294319, 2022). "Besides, SOX4 expression in colon cancer tissues and the correlation between SOX4 and LEMD1 were examined using the GEPIA database." (PMID 35294319, 2022).
thyroid cancer (2 papers, 2022). "According to public data from GEPIA, LEMD1 was frequently upregulated in multiple kinds of malignant tumors, such as OV (ovarian serous cystadenocarcinoma), CESC (cervical squamous cell carcinoma) and THCA (thyroid carcinoma)." (PMID 35286235, 2022).
anaplastic large cell lymphoma (1 paper, 2022). Anaplastic large cell lymphoma (ALCL) is a rare and aggressive peripheral T-cell non-Hodgkin lymphoma, belonging to the group of CD30-positive lymphoproliferative disorders, which affects lymph nodes and extranodal sites. "LEMD1 is also the target gene of microRNA-135 in anaplastic large cell lymphoma." (PMID 35983249, 2022).
breast carcinoma (1 paper, 2023). "In the previous screening process of the target gene, we found that the high expression of LEMD1 was associated with anti-cancer drug resistance in breast cancer cell lines via genomic analysis, which inspired us to explore the role of LEMD1 in chemotherapy resistance." (PMID 37296887, 2023). "In this study, we demonstrated for the first time that LEMD1 is highly expressed in TNBC and is associated with poor prognosis in breast cancer patients." (PMID 37296887, 2023). "Firstly, data from an independent breast cancer dataset consistently shows that LEMD1 is significantly upregulated in TNBC tumors compared to non-TNBC tumors." (PMID 37296887, 2023). "Next, we confirmed LEMD1 expression in breast cancer tissues." (PMID 37296887, 2023). "Considering the role of LEMD1 in breast cancer remains unknown, we further explored the biologic function and the clinical value of LEMD1 in TNBC." (PMID 37296887, 2023). "In addition, the low expression of LEMD1 was positively correlated with improved survival in breast cancer patients, as shown by analysis of the clinical data of 85 patients we collected." (PMID 37296887, 2023). "Since LEMD1 is one of the family members of cancer testis antigen that is often regulated by DNA demethylation, as reported, we analyzed the methylation level of LEMD1 in breast cancer." (PMID 37296887, 2023). "Moreover, higher protein expressions of LEMD1 were observed in TNBC tissues compared to non-TNBC tissues in a tissue microarray (TMA) containing 80 breast cancer specimens we collected from the Second Xiangya Hospital." (PMID 37296887, 2023). "Nevertheless, the biological function of LEMD1 in breast cancer has not been elucidated yet." (PMID 37296887, 2023). "LEMD1 is hypomethylated in breast cancer tissues compared with normal tissues, and its hypomethylation was positively correlated with reduced disease-free interval (DFI) in breast cancer patients." (PMID 37296887, 2023).